P4HA3 (prolyl 4-hydroxylase subunit alpha 3)
Diseases named in the same sentence as P4HA3 in open-access papers (continued):
Sharing a sentence is not in itself a finding about the gene and the disease.
cancer (continued). "To explore the clinical significance of P4HA3 among different tumors, we evaluated P4HA3 mRNA expression profile across TCGA and GTEx cancers by using the TIMER 2.0 and SangerBox tools." (PMID 39504328, 2024). "The heat map showed that P4HA3 was significantly positively correlated with the expression of these EMT markers in various of cancers, especially in COAD." (PMID 39504328, 2024). "In NSCLC, TGF-β pathway altered the amino acid metabolism and induced EMT happen by increasing P4HA3 expression, consequently contributed to cancer cell malignant progression." (PMID 39504328, 2024). "It was indicated that P4HA3 was mainly enriched in the cytokine-cytokine receptor, interaction pathways in cancer and the functions of extracellular matrix structural constituent." (PMID 37957566, 2023). "The study also showed that P4HA3 was significantly negatively correlated with nine different cancer-related functional statuses in GBM and UM, respectively." (PMID 37035741, 2023). "Our findings suggest that P4HA3 is expressed at high levels in most cancers, which correlates with the spite of cancers and poor prognosis." (PMID 37035741, 2023). "In this study, we evaluated the expression of P4HA3 and its relationship with the prognosis of cancer patients." (PMID 37035741, 2023). "Prolyl 4-hydroxylase subunit alpha 3 (P4HA3) has been known by people that it has a relationship with many kinds of human cancers." (PMID 35433237, 2022). "The most predominant ECM regulators, ADAM12, MMP1, SERPINE1, PLOD3, and P4HA3, have been classified as a five‐gene signature that produces a broad effect over 29 types of cancer." (PMID 34121340, 2021). "As a comparison, SERPINE1 was upregulated in 8 out of 12 cancer types (p < 0.05) and P4HA3 was 12 of 14 cancer types (p < 0.05)." (PMID 34121340, 2021). "In general, the mRNA expression levels of ADAM12, MMP1, SERPINE1, PLOD3, and P4HA3 were correlated with immune infiltration score and macrophages and dendritic cells (DCs) in most types of cancer." (PMID 34121340, 2021). "The ECM‐receptor interaction gene set was further analyzed for correlation with ADAM12, MMP1, SERPINE1, PLOD3, and P4HA3 in the 29 cancer types." (PMID 34121340, 2021). "In the xenografted tumors both P4HA1 and P4HA2 mRNA are found at similar levels in cancer cells and in stroma, contrasting the stroma-specific expression of P4HA3." (PMID 27809802, 2016). "Because the expression of P4HA3 was up-regulated in various of tumors and correlated with worse survival prognosis, we thought that P4HA3 possibly become a new therapeutic target for cancers." (PMID 39504328, 2024). "This pan-cancer analysis of P4HA3 provides a comprehensive understanding of its oncogenic and prognosis role in different cancers, P4HA3 abnormal expression could be a useful biomarker for predicting the effectiveness of immunotherapy in cancer patients." (PMID 39504328, 2024). "Notably, in this study, we also found a significant positive correlation between the degree of CAFs infiltration and P4HA3 expression in pan-cancer." (PMID 37035741, 2023). "In addition, we analyzed the relationship between the expression of P4HA3 and the clinicopathological stage of cancer." (PMID 37035741, 2023). "Thus, the expression level of P4HA3 correlated with the clinicopathological stage, immune subtypes, and molecular subtypes of cancer." (PMID 37035741, 2023). "In addition, gene set enrichment analysis (GSEA) was used to explore the potential functional mechanisms of P4HA3 in pan-cancer." (PMID 37035741, 2023). "Prolyl 4-hydroxylase (P4H) activity is essential for maintenance of the collagen triple helix and P4HAs (P4HA1, P4HA2, P4HA3) plus P4HB are highly expressed in numerous tumors where they may contribute to cancer progression." (PMID 35846138, 2022). "Also, P4HA3 manifested a cancer promoter through the regulation of EMT in the head and neck squamous cell cancer." (PMID 35433237, 2022).
cancer (continued). "Multiple researches have been conducted to report the correlation on P4HA3 with various cancers." (PMID 35433237, 2022). "The protein expression levels of PLOD3 and P4HA3 were high in most cancer tissues." (PMID 34121340, 2021). "In summary, we demonstrated that EMT inducers, such as TGF-β, alter amino acid metabolism by inducing P4HA3 expression, which might consequently contribute to cancer cell malignant properties in vitro and in vivo." (PMID 34168290, 2021). "In the 18 cancer types from TCGA, we calculated tissues with mutations of ADAM12, MMP1, SERPINE1, PLOD3, and P4HA3, and they had limited mutations, and their mutation sites had few significant effects on gene expression or function gain across the 18 cancer types." (PMID 34121340, 2021). "Furthermore, we assessed the effect of P4HA3 knockdown on cancer metastasis using a tail vein injection model." (PMID 34168290, 2021). "P4HA3 was the only mRNA that was expressed at higher levels in cancer compared to normal breast tissue following adjustment for the ECM metagene and it was one of the genes that were significantly associated with prognosis in the multivariate models in both microarray sets." (PMID 27809802, 2016). "Following this adjustment only P4HA3 was higher in cancer tissue." (PMID 27809802, 2016). "Therefore, in this study, we systematically analyzed the expression of P4HA3 in various cancers." (PMID 37035741, 2023). "This study may provide ideas for future researchers to study the role of P4HA3 in human cancers." (PMID 37035741, 2023). "In addition, although the present study identified that P4HA3 might affect cancer by participating in some potential signaling pathways, the specific molecular biology of the mechanism of action is not yet clear." (PMID 37035741, 2023). "We explored the relationship between P4HA3 expression profile and prognosis value, genetic alteration, epigenetic regulation and TME among different cancers." (PMID 39504328, 2024). "Materials and methods: First, the expression profile of P4HA3 was analyzed using a combination of the University of California Santa Cruz (UCSC) database, Cancer Cell Line Encyclopedia (CCLE) database, and Genotype-Tissue Expression (GTEx) database." (PMID 37035741, 2023). "Further analysis of the correlation between these key genes and the pathological stage of GC showed that COL1A1, COL5A2, P4HA3, and SPARC were significantly correlated to cancer pathological stages." (PMID 35368700, 2022). "As a result, the higher protein expression levels of ADAM12, PLOD3, P4HA3, and SERPINE1 were detected in multiple types of cancer compared with the normal tissue specimens, which was consistent with their mRNA expression patterns." (PMID 34121340, 2021). "Additionally, a P4HA3 inhibitor may be a potential anti-cancer agent." (PMID 34168290, 2021). "However, the role and mechanism of P4HA3 in the malignant tumors was largely unknown." (PMID 31627190, 2019). "The 95 % confidence intervals of the hazard ratios of P4HA3, SRPX2, DCN, OMD, and TCF4 all excluded 1 in multivariate analysis in both cancer sets." (PMID 27809802, 2016). "We found that P4HA3 expression was positively correlated with the typical proliferation proteins, including proliferating cell nuclear antigen (PCNA) and Ki-67 in various of cancers, such as BLCA, BRCA, HNSC, KICH by the heat map (P < 0.05)." (PMID 39504328, 2024). "We found that there was negative correlation between DNA methylation and P4HA3 expression in cancers, especially in HNSCC, COAD, OV, THYM, SKCM, KIRP and SARC." (PMID 39504328, 2024). "The role of P4HA3 in regulating TME and cancer progression need more research to confirm." (PMID 39504328, 2024). "We found that the remarkable negative correlation with DNMTs and P4HA3 expression level in 33 types of cancers." (PMID 39504328, 2024). "Finally, P4HA3-related drugs were searched in CellMiner, Genomics of Drug Sensitivity in Cancer (GDSC), and Cancer Therapeutics Response Portal (CTRP) databases." (PMID 37035741, 2023).
cancer (continued). "The previous research found that the expression levels of both P4HA3 mRNA and protein of gastric cancer tissues were obviously increased compared with nongastric cancer tissues." (PMID 35433237, 2022). "However, further studies are warranted to reveal whether P4HA3 upregulation is epigenetically regulated during EMT, whether P4HA3 rewires amino acid metabolism via regulation of the urea cycle, and how TGF-β-induced loss of amino acids contributes to EMT in cancer cells." (PMID 34168290, 2021). "We explored the possible correlation between P4HA3 expression level and the infiltrating immune and stromal cells by using the ESTIMATE algorithm, and found that P4HA3 expression was prominently correlated with immune score, stromal score and ESTIMATE score in various of cancers." (PMID 39504328, 2024). "However, the relationship between P4HA3 and TME in various of cancers is largely unknown." (PMID 39504328, 2024). "However, P4HA3 has not been reported in other cancers, and the exact mechanism of action is currently unknown." (PMID 37035741, 2023).
P4HA3 also shares sentences with these, for which no sentence is quoted: type 2 diabetes mellitus (2 papers); achondroplasia (1); adrenocortical carcinoma (1); Alzheimer disease (1); atrial fibrillation (1); breast invasive carcinoma (1); breast tumor (1); cardiovascular disease (1); cervical squamous cell carcinoma (1); cholangiocarcinoma (1); colorectal cancer (1); genetic disorder (1); mesothelioma (1); metabolic disorder (1); metastatic melanoma (1); ovarian serous cystadenocarcinoma (1); premature ovarian failure (1); skin cutaneous melanoma (1); squamous cell carcinoma (1); stomach adenocarcinoma (1); testicular germ cell tumor (1); thyroid carcinoma (1); uterine corpus endometrial carcinoma (1).